ACE (angiotensin I converting enzyme)
Diseases named in the same sentence as ACE in open-access papers (continued):
Sharing a sentence is not in itself a finding about the gene and the disease.
Hypertension (continued). "Despite HD and PD having different pathophysiology involved, compliance with medications such as warfarin therapy in AF, ACE inhibitors, statins in patients with myocardial infarction, congestive heart failure, diabetes and hypertension control, and clopidogrel is required for better survival." (PMID 32874811, 2020). "ACE then hydrolyzes AT-1 by cleaving the carboxyl terminal His-Leu dipeptide from the inactive AT-1 to the active angiotensin II (AT-2), a potent vasoconstrictor responsible for the development of hypertension." (PMID 32013233, 2020). "The use of AT1R blockers and ACE inhibitors is encouraged in hypertensive patients because these drugs are vasoprotective, and their associated increase in ACE2 expression (see the paragraph below) protects against hypertension." (PMID 33195477, 2020). "Pharmacological agents targeting the RAS pathway and, specifically, the synthesis of Ang II (ACE inhibitors) or Ang II receptor signaling (Ang II receptor blockers or ARBs) are effective in reversing hypertension-induced vascular remodeling in conductive and resistance arteries." (PMID 33195477, 2020). "In any case, discontinuation of ACE-Is/ARBs in hypertension patients with COVID-19 might further decrease ACE2 levels, therefore worsening disease prognosis." (PMID 32575076, 2020). "ACE then converts Ang-I to Ang-II, which is a primary drug target for patients with hypertension." (PMID 32501190, 2020). "While scientist are working to find a vaccine, current epidemiological data shows that the most common comorbidities for patients with the worst prognosis, hypertension and diabetes, are often treated with angiotensin converting enzyme (ACE) inhibitors and angiotensin receptor blockers (ARBs)." (PMID 32835160, 2020). "People with co-morbidities, including diabetes and hypertension, who are treated with the drugs such as thiazolidinediones, angiotensin-converting enzyme (ACE) inhibitors, and angiotensin-II receptor blockers (ARBs) have an increased expression of angiotensin-converting enzyme-2 (ACE-2)." (PMID 33014977, 2020). "A pioneering example was the development of Captopril® from a peptide discovered in the venom of the Brazilian pit viper Bothrops jararaca, and subsequent development of angiotensin-converting enzyme (ACE) inhibitors that have had a significant impact in hypertension control since the 1980s." (PMID 32326531, 2020). "Currently, pharmaceutical drugs such as angiotensin-converting enzyme (ACE) inhibitors and angiotensin (Ang) II type 1 receptor (AT1R) blockers are the first-line therapy for hypertension, but they are associated with various adverse effects such as dry cough and angioedema over a prolonged use." (PMID 33019511, 2020). "The following variables were demonstrated to be associated with a worse prognosis: Radiologic Brixia score higher than 8, presence at baseline of hypertension, diabetes, chronic obstructive pulmonary disease, heart disease, cancer, previous treatment with ACE-inhibitors or anti-platelet drugs." (PMID 33201172, 2020). "Therefore, ACE (EC 3.4.15.1) and/or renin inhibition help to manage hypertension and offer cardiovascular protection by limiting the physiological level of angiotensin II." (PMID 32610462, 2020). "Hypertension is the key modifiable risk factor for stroke, systemic RAS blockade, with ACE inhibitors (ACEi) or Ang II type 1 receptor (AT1R) antagonists (angiotensin receptor blockers; ARBs), is a common therapy for treating hypertension and with efficient BP control the risk of stroke is reduced." (PMID 33059037, 2020). "Because of this, most hypertension drugs target vascular smooth muscles to lower blood pressure, such as angiotensin-converting enzyme (ACE) inhibitors, angiotensin receptor blockers (ARBs), β-blockers, and calcium channel blockers (CCBs), and these drugs are used singly or in combination." (PMID 31894475, 2020).
Hypertension (continued). "Moreover, in a retrospective review of 42 hospitalized COVID-19 patients with hypertension (median age 64), 17 subjects received ACE inhibitors (ACEi) or ARB therapy and 25 subjects received other antihypertensive drugs." (PMID 32922297, 2020). "Franquni M. and colleagues showed that myocyte hypertrophy and cardiac remodeling (ND related) are related to augmentation of ACE activity and the development of a pro-inflammatory state, and consequent cardiac changes result in the development of hypertension in animals treated with ND." (PMID 33187340, 2020). "ACE inhibitors are agents commonly used for the treatment of hypertension and heart failure." (PMID 32586380, 2020). "In univariate analysis, odds of ICU care/death were higher in males, and those with higher BMI, older age, a history of diabetes or hypertension, and chronic medication such as steroids, angiotensin-converting enzyme (ACE) inhibitors or angiotensin II receptor blockers (ARBs)." (PMID 33317458, 2020). "Furthermore, Peril, a classical ACE inhibitor, is used to treat hypertension by blocking the conversion of Ang I to Ang II and decreasing the expression of Ang II." (PMID 32184813, 2020). "In hypertension, there is an increase of angiotensin-converting enzyme (ACE)." (PMID 33101440, 2020). "In this review, we described the two-way switch role of ACE2 in the treatment of novel coronavirus pneumonia and underlying comorbidities, and discussed the potential effect of the ACE inhibitor and angiotensin receptor blocker on a hypertension patient with the SARS-CoV-2 infection." (PMID 33396184, 2020). "Patient-related risk factors include advanced age, history of AF, history of HF, renal failure, hypertension, chronic obstructive pulmonary disease, post-operative withdrawal or absence of beta-blocker, or angiotensin-converting enzyme inhibitor (ACE inhibitor) therapy." (PMID 32538434, 2020). "Almost all participants with diabetes also had hypertension with differentially high uptake of reno protective drugs such as angiotensin converting enzyme (ACE) inhibitors and angiotensine receptor inhibitors among those with diabetes at baseline (in line with guidelines)." (PMID 32188410, 2020). "Therefore, ACE has long been a major target for the treatment of hypertension and other cardiovascular ailments by the use of ACE inhibitors." (PMID 32178362, 2020). "Treatments with antihypertensive drugs (i.e., alpha-2 agonists, diuretics, beta-blockers, calcium channel blockers, and ACE inhibitors) registered in the Danish Register of Prescribed Drugs and inpatient hypertension diagnoses recorded in the national hospital discharge register were considered." (PMID 32872306, 2020). "ACE suppression is considered as an essential approach in regulating hypertension." (PMID 32012183, 2020). "However, it has been proposed that when patients with heart failure and hypertension receive ACE inhibitors and type-I receptor blockers (ARBs), these agents contribute to the upregulation of ACE2 receptors." (PMID 32825068, 2020). "The ACE function could induce the vasoconstriction and progression of hypertension and related pathological manifestations." (PMID 32012183, 2020). "It has been postulated that the progression of COVID-19 into severe COVID-19 in patients with hypertension may be due to prior and concomitant use of angiotensin converting enzyme (ACE) inhibitors or angiotensin II receptor blockers (ARBs)." (PMID 33199670, 2020). "Consequently, ACE-inhibiting natural products have been vigorously investigated during the last decades, due to their potential in lowering blood pressure during hypertension." (PMID 32013233, 2020). "In patients using ACE inhibitors or angiotensin II receptor blockers (ARBs) for hypertension, upregulated ACE2 expression impacts on disease course remains unclear." (PMID 32963831, 2020).
Hypertension (continued). "One of the therapeutic methods for hypertension treatment is the use of ACE inhibitors, since reduction of the concentration of the most important vasoconstrictor (angiotensin II) by suppressing ACE is a key factor to achieve blood pressure balance and water balance in the body." (PMID 32471271, 2020). "ACE-Inhibitor induced cough in our study was more frequent with increasing age in years, which is reasonably explained by the fact that indications of ACE-Inhibitors e.g. hypertension and heart disease are usually more common with increased age." (PMID 32292434, 2020). "Thus, ACE inhibitors, ARBs, and mineralocorticoid receptor antagonists are the standard therapy in hypertension and myocardial infarction." (PMID 33195477, 2020). "The recent reports of hypertension as a comorbidity in COVID-19 patients and specifically the use of ACE inhibitors as antihypertensives contributing to mortality encourages a hypothesis-free examination of the FDA adverse event reporting system (FAERS)." (PMID 32463365, 2020). "Therefore, sesame protein would be an attractive raw material generating ACE inhibitory peptides for controlling hypertension." (PMID 32033479, 2020). "Both cow's milk and soy milk kefir showed significant ACE inhibitory activity, a factor that may be beneficial for people with high blood pressure." (PMID 32565815, 2020). "The Prescribed Drug Register could identify individuals with hypertension or high blood pressure as it includes information on individuals that dispensed a medication regularly used to treat these conditions (diuretics, beta-blockers, ACE inhibitors etc.)." (PMID 32424571, 2020). "We further hypothesize that bioactive peptide VHVV might be used as an alternative drug to commercial drug ACE inhibitors for preventing hypertension-mediated impairment." (PMID 31234585, 2019). "This may be consistent with either a positive action of hemorphins (hypertensive) through targeting AT1R because of the exercise or their negative regulatory effect (hypotensive) through the inhibition of ACE to avoid any excessive hypertension." (PMID 31708782, 2019). "Anti-ACE fish biopeptides, similar to other bioactives, mostly exert their effect on the subject non-cytotoxically, negligible and or zero cytotoxicity, making them superior to the synthetic drugs for treatment and prevention of hypertension." (PMID 31671730, 2019). "However, the increase in oxidative stress parameters was observed to be the most significant in patients with COPD+hypertension, and with the I/I genotype of the ACE gene, which was due to their lowest values in virtually healthy individuals." (PMID 32025262, 2019). "Therefore, ACE inhibitors, such as captopril, lisinopril and enalapril, are widely used as pharmaceutical drugs for the treatment of hypertension." (PMID 31100914, 2019). "Angiotensin I-converting enzyme (ACE) plays a key role in controlling hypertension." (PMID 31086041, 2019). "Thus, ACE inhibitors have been used as essential therapeutic agents for cases of systemic hypertension." (PMID 31234939, 2019). "Angiotensin converting enzyme (ACE) inhibitors have shown beneficial effects on endothelial function in patients with hypertension and other cardiovascular diseases, however there are few studies evaluating the effect of treatment with this class on the reduction of C-reactive protein (CRP) levels." (PMID 31337127, 2019). "Therefore, our study aimed to establish the role of polymorphism in the angiotensin-converting enzyme (ACE) and angiotensinogen (AGT) genes in the mechanisms behind the development of oxidative stress in patients with concomitant COPD and hypertension." (PMID 32025262, 2019). "This suggested that an ACE-inhibitor could be derived from a cobia skin protein hydrolysate and used to develop functional products that could be used for the prevention of hypertension." (PMID 31208053, 2019).
Hypertension (continued). "Indeed, AT1R blockers and inhibitors of AngII production (ACE inhibitors) are now extensively used in the treatment of hypertension and other cardiovascular diseases." (PMID 31447777, 2019). "Pharmacological medications such as angiotensin converting enzyme (ACE) inhibitor for hypertension, statins for hyperlipidemia, metformin, and glybenclamide for hyperglycemia have been successfully developed and used for the treatment of each component in Mets." (PMID 30854019, 2019). "ACE plays a primary role in the rennin angiotensin and kinin-kallikrein systems by increasing the production of angiotensin II and decreasing the formation of bradykinin thereby resulting in hypertension." (PMID 31145747, 2019). "Although the ACE D/I polymorphism is considered nonfunctional by some authors, its relationship with several pathophysiological conditions such as hypertension, atherosclerosis and coronary heart disease is extensively discussed in the literature." (PMID 31365628, 2019). "The mechanism by which hypertension may prolong CSU is, however, unclear although it should be borne in mind that ACE inhibitors used in hypertension can aggravate and prolong CSU." (PMID 31528163, 2019). "The development of new functional foods bonded with ACE inhibitory peptides from natural protein sources may be an important part of the prevention against hypertension." (PMID 31487872, 2019). "As a rich source of protein (79.1% protein content on dry basis), the pearl oyster meat could act as a potential source of ACE inhibitory peptides for the functional foods against hypertension." (PMID 31398788, 2019). "One limitation of using an ACE inhibitor to assess the contribution of AngII to hypertension in BPH/2 mice is that ACE inhibitors also reduce the degradation of bradykinin, which itself could have a vasodilatory effect." (PMID 31681017, 2019). "In addition, hypertension is also related to angiotensin-I-converting enzyme (ACE), which is involved in vascular tension." (PMID 31531114, 2019). "In the case of a pathological situation, the high expression/activity of AT1R associated with a plausible decrease in ACE expression/activity and the high release of hemorphins may be symptomatic of the pathophysiology of RAS and hypertension." (PMID 31708782, 2019). "Higher ACE inhibition means lower conversion of angiotensin I to angiotensin II, a potent vasoconstrictor, and it seems to be a strategic treatment to protect against hypertension—which is a representative complication of diabetes." (PMID 31615144, 2019). "Therefore, SHR rats fed 8% salt diet is a hypertension model that is resistant to ACE inhibitors and AT1 receptor blockers, as also demonstrated in this study using captopril and losartan, respectively." (PMID 30530571, 2019). "Most participants had hypertension (89.2%), and mean office systolic/diastolic BP was 142.2/79.0 mmHg; 68.2% of patients were taking angiotensin II receptor blockers (ARBs) and 4.7% were taking angiotensin-converting enzyme (ACE) inhibitors." (PMID 31455298, 2019). "In addition, the evaluation of ACE inhibitory activity reveal the potential possibility of these peptides to treat hypertension." (PMID 31487872, 2019). "Three-mixed juice, which shows high ACE inhibitory activity, may be useful as an anti-hypertensive agent and for treating hypertension." (PMID 31093447, 2019). "The need to regulate hypertension has led to the development of ACE inhibitors." (PMID 31137657, 2019). "The results obtained in this study indicate that the combination of genetic polymorphisms of ACE and ACE2 may contribute to the development of hypertension, with the DD/G_ combination being the susceptibility profile." (PMID 31430320, 2019). "Among diabetic patients, the two most frequent interactions were between angiotensin II receptor antagonists and ACE inhibitors with diuretics to treat hypertension, which are interactions of similar mechanisms, due to the pharmacodynamics of the classes involved." (PMID 31460618, 2019).
Hypertension (continued). "In conclusion, we have demonstrated that PASE has the long-acting anti-hypertension effect and ACE inhibition may be the mechanism of PASE antihypertensive activity." (PMID 31114496, 2019). "Here we evaluated the effects of corn silk tea on ACE activity in vitro and hypertension in SHRs." (PMID 31100914, 2019). "Nevertheless, analysis of a very large UK Biobank that was recently made available revealed an association between polymorphisms in RAAS genes and hypertension-related traits at the significant threshold level of 5 × 10−8, e.g., rs699 in AGT with both SBP and DBP and rs4308 in ACE with DBP." (PMID 31511791, 2019). "ACE inhibitors such as perindopril, enalapril, and ramipril are widely used to treat hypertension." (PMID 31739443, 2019). "Recent data showed that many drugs may affect the IGF system like ACE inhibitors (drugs are used for management hypertension) and statins (drugs are used for management dyslipidemia)." (PMID 31354810, 2019). "Besides the activation of Ag II, ACE plays a concomitant role in the regulation of hypertension via the inactivation of an endothelium-dependent vasodilatory peptide, bradykinin." (PMID 31137657, 2019). "Hence, inhibition of ACE is considered a major therapeutic approach in the treatment of hypertension and cardiovascular disease." (PMID 31114496, 2019). "This study provides evidence that age, BMI, diabetes, preference for fried or barbecued foods and polymorphism in the ACE, ATR, and CYP11B2 genes of the RAAS system were associated with elevated risk of hypertension among Hui Hajj pilgrims in Gansu Province, China." (PMID 31484569, 2019). "However, interventions with ACE-targeting antibodies have led to hypertension, cough, and edema while targeting thrombomodulin can trigger thrombosis." (PMID 30854484, 2019). "We speculated that miso with potent ACE inhibitory activity attenuates hypertension to a greater extent than regular commercially available miso, particularly hypertension associated with enhancement of the renin–angiotensin system (RAS)." (PMID 30631160, 2019). "Angiotensin I-converting enzyme (ACE) is a paramount therapeutic target to treat hypertension." (PMID 31336853, 2019). "This could imply that a very large sample size might be required to have an adequate statistical power to detect association in hypertension-related traits, such as shown in AGT and ACE genes." (PMID 31511791, 2019). "Finally, the analysis of the influence of combined ACE and ACE2 polymorphisms in treatment response profile on hypertension and CVD can be of great help for personalized medicine if the findings of this study were confirmed by other researchers." (PMID 31430320, 2019). "Epidemiological studies have suggested that angiotensin converting enzyme (ACE) inhibitors which are used to treat hypertension and cardiac failure (common comorbidities of COPD), may benefit COPD, by reducing mortality and exacerbations." (PMID 31636311, 2019). "Captopril was the first orally active ACE inhibitor approved to treat human hypertension." (PMID 31683604, 2019). "An ACE inhibitor is used primarily for the treatment of hypertension and congestive heart failure." (PMID 31198910, 2019). "Some of the most effective medications for the treatment of hypertension are ACE inhibitors." (PMID 31683604, 2019). "His past medical history was characterized by multiple myeloma, Gilbert syndrome, chronic obstructive pulmonary disease (COPD) treated with bronchodilators, cardiac arrhythmia treated with amiodarone, and arterial hypertension treated with angiotensin-converting enzyme (ACE) inhibitors." (PMID 30836992, 2019). "Therefore, the aim of this meta-analysis is to pool the available evidence and provide insights into the potential linkage(s) between the ACE gene and its effect on treatment and pathogenesis of hypertension in individuals of African origin." (PMID 30763326, 2019).